MIR548AV (microRNA 548av)
Synonyms: hsa-mir-548av
Gene: MicroRNA gene on chromosome 18 (72,853,321 to 72,853,382, reverse strand). Ensembl gene ENSG00000263750.
Homologues: Paralogues in human: MIR548K (66% identical), MIR548S (66% identical), MIR548O2 (65% identical), MIR548P (63% identical), MIR548AQ (61% identical), MIR548AZ (61% identical), MIR548X (61% identical), MIR548AY (60% identical), MIR548F3 (60% identical), MIR548H5 (60% identical), MIR548AA1 (58% identical), MIR548H3 (58% identical), and 13 more.